RPL36A (ribosomal protein L36a)
Description:
Component of the large ribosomal subunit. The ribosome is a large ribonucleoprotein complex responsible for the synthesis of proteins in the cell.
Synonyms: RPL44; MIG6; L36A; eL42; L44L
Tractability: Small molecule: an approved drug acts on it; a structure with a bound ligand is known; a high-quality ligand is known. Antibody: its Gene Ontology location is reachable by antibodies, with high confidence. PROTAC: ubiquitination databases record sites on it; its protein half-life has been measured; a small molecule that binds it is known. Other modalities: a drug acting on it is in phase 2 or 3 trials.
Gene: Protein-coding gene on chromosome X (101,390,824 to 101,396,155, forward strand). Ensembl gene ENSG00000241343.
Subcellular location: Cytoplasm
Subcellular location (Human Protein Atlas): Cytosol; Endoplasmic reticulum; Plasma membrane
Pathways (Reactome):
Metabolism of proteins: Eukaryotic Translation Termination; Formation of a pool of free 40S subunits; GTP hydrolysis and joining of the 60S ribosomal subunit; L13a-mediated translational silencing of Ceruloplasmin expression; PELO:HBS1L and ABCE1 dissociate a ribosome on a non-stop mRNA; Peptide chain elongation; Ribosome Quality Control (RQC) complex extracts and degrades nascent peptide; SRP-dependent cotranslational protein targeting to membrane; ZNF598 and the Ribosome-associated Quality Trigger (RQT) complex dissociate a ribosome stalled on a no-go mRNA
Metabolism of RNA: Major pathway of rRNA processing in the nucleolus and cytosol; Nonsense Mediated Decay (NMD) enhanced by the Exon Junction Complex (EJC); Nonsense Mediated Decay (NMD) independent of the Exon Junction Complex (EJC)
Cellular responses to stimuli: Response of EIF2AK4 (GCN2) to amino acid deficiency
Developmental Biology: Regulation of expression of SLITs and ROBOs
Disease: Viral mRNA Translation
Metabolism: Selenocysteine synthesis
Gene Ontology:
Molecular function: protein binding; RNA binding; structural constituent of ribosome
Biological process: cytoplasmic translation; negative regulation of myoblast fusion; striated muscle contraction; translation
Cellular component: cytoplasm; cytosol; cytosolic large ribosomal subunit; cytosolic ribosome; endoplasmic reticulum; ribosome
Homologues: Orthologues: chimpanzee HNRNPH2 (100% identical), dog RPL36AL (100% identical), guinea pig Rpl36al (100% identical), mouse Rpl36al (100% identical), pig RPL36AL (100% identical), rat Rpl36al1 (100% identical), chimpanzee RPL36AL (99% identical), tropical clawed frog rpl36a (96% identical). Paralogues in human: RPL36AL (99% identical).
Diseases named in the same sentence as RPL36A in open-access papers:
RPL36A is named in the same sentence as 20 diseases in open-access papers, as found by Europe PMC text mining. Sharing a sentence is not in itself a finding about the gene and the disease. The quoted sentences say what the papers report.
hepatocellular carcinoma (9 papers, 2006 to 2025). A malignant tumor that arises from hepatocytes. "Expression analysis revealed significant differences and upregulation of RPL36A in various tumours, including breast cancer, renal clear cell carcinoma, hepatocellular carcinoma, pancreatic cancer and lung cancer, compared to normal tissues." (PMID 40008552, 2025). "Pan‐cancer analysis of RPL36A expression revealed significant differences across various tumour types, including hepatocellular carcinoma, breast cancer, colon cancer and NSCLC, compared to normal tissues." (PMID 40008552, 2025). "For instance, RPL36A, which was overexpressed in the microarray analysis, is upregulated in hepatocellular carcinoma and has been shown to increase cell proliferation." (PMID 34968392, 2021). "Overexpression of ribosomal protein L36a (RPL36A) has been reported to closely relate to cellular proliferation in hepatocellular carcinoma." (PMID 33133154, 2020). "Since RPL36A is overexpressed in hepatocellular carcinoma and confers radioresistance to oral squamous cell carcinoma, we determined whether the expression of ribosomal genes is altered by polyamines using the results of the proteomic analysis." (PMID 40617352, 2025). "RPL36A over-expression is found in hepatocellular carcinoma." (PMID 29179492, 2017).
glioma (4 papers, 2017 to 2023). A benign or malignant brain and spinal cord tumor that arises from glial cells (astrocytes, oligodendrocytes, ependymal cells). "RPL36A gene is involved in tumour cell proliferation and associated with gliomas." (PMID 36528847, 2023). "Only RPS11 and RPL36A were previously found to be beneficial in glioma as prognostic predictors." (PMID 36497269, 2022). "A 20-gene signature was identified, which was associated with radiotherapy.Furthermore, a novel 5-gene signature (HOXC10, LOC101928747, CYB561D2, RPL36A and RPS4XP2) as an independent predictor of glioma patients’ prognosis was further derived from the 20-gene signature." (PMID 29179492, 2017).
breast carcinoma (3 papers, 2020 to 2025). "TCGA data showed that high levels of these RPs were associated with high survival probability in breast cancer patients, and excepted RPL36A, their expression levels were suppressed." (PMID 32483207, 2020). "Thus, we confirmed that the expression level of the RPL36A protein was also decreased in polyamine-depleted HeLa S3 cells and breast cancer cell lines." (PMID 40617352, 2025).
rhabdomyosarcoma (2 papers, 2021 to 2023). A rare aggressive malignant mesenchymal neoplasm arising from skeletal muscle. "Additionally, eL36/RPL36 and eL42/RPL36A mRNA levels in rhabdomyosarcoma were less than half of the mRNA level in the skeletal muscle fibroblasts, suggesting strong translational control." (PMID 37047306, 2023). "Relative to skeletal muscle fibroblasts, several rhabdomyosarcoma cell lines (RH18, RH28, RH36, RH41, RD, and Kym-1) showed higher levels of eL36/RPL36 and eL42/RPL36A, while uL18/RPL5 remained unchanged." (PMID 37047306, 2023).
autism (1 paper, 2022). Persistent deficits in social interaction and communication and interaction as well as a markedly restricted repertoire of activity and interest as well as repetitive patterns of behavior. "This is in line with the present observation on the upregulation of RPL36A in autistic patients and indicates that the upregulation of RPL36A can influence the development of autism through the dysfunction of SHANK3-associated synaptopathies." (PMID 35215271, 2022). "Defects in the SH3 and multiple ankyrin repeat domains 3 (Shank3) protein cause numerous synaptopathies, including autism; upregulation of the RPL36A was reported in the striatal synaptosome of Shank3-overexpressing transgenic mice." (PMID 35215271, 2022).
duodenal cancers (1 paper, 2022). "Meanwhile, several upregulated genes in CRC malignant cells such as RPLP2, RPL36A, TFF3 have the increasing expression tendency in malignant cells from GC, duodenal cancers, jejunal cancers to CRC." (PMID 36104333, 2022).
Infertility (1 paper, 2021). "The association of RPL36A with infertility has been reported." (PMID 34738918, 2021).
kidney tumor (1 paper, 2020). "However, the antibody staining level of EEF1A2 and RPL36A were decreased from normal tissue to kidney tumor tissue." (PMID 33133154, 2020).
lung carcinoma (1 paper, 2025). "Notably, RPL36A emerged as a potential tumour marker for NSCLC, with its expression validated in lung cancer cell lines through qPCR." (PMID 40008552, 2025).
Obesity (1 paper, 2025). Accumulation of substantial excess body fat. "Obesity also consistently altered 5 proteins in DMBA-exposed mice, including HNRNPC, HNRNPD, HSPA9, RPL36A, and KCTD12." (PMID 39910959, 2025).
cancer (7 papers, 2016 to 2025). A tumor composed of atypical neoplastic, often pleomorphic cells that invade other tissues. "In the gene cluster exhibiting a consistent positive dysregulation score in distinct cancer types (red line) we identified proteins that have been previously associated with increased proliferation phenotypes, such as RPL36A and RPS2." (PMID 27884178, 2016). "In the cluster of RPs that have positive dysregulation scores across distinct cancers we identified several proteins, some of which had been previously associated with increased proliferation phenotypes, such as RPL36A and RPS2." (PMID 27884178, 2016). "Additionally, RPL36A expression showed significant variation among patients at different cancer stages." (PMID 40008552, 2025). "In addition, polyamines upregulated the expression of five ribosomal proteins, particularly RPS27A, RPL36A, and RPL22L1, which are associated with cancer malignancy." (PMID 40617352, 2025). "Experiments are in progress to clarify the polyamine-stimulatory mechanisms of eIF5A1, PKM, RPL36A, and RPL22L1 synthesis and functions of RPL36A and RPL22L1 during translation elongation in cancer cells." (PMID 40617352, 2025).
tumor (6 papers, 2017 to 2025). "It is likely that RPL36A influences patient outcomes beneficially by modulating other genes or pathways that inhibit tumour growth." (PMID 40008552, 2025). "The complexity of the role of RPL36A highlights the need for further investigation into how this gene interacts within the tumour microenvironment and contributes to therapeutic responses." (PMID 40008552, 2025). "However, TCGA data analysis showed increased RPL36A expression in tumour tissues, a finding supported by qPCR validation." (PMID 40008552, 2025). "This discrepancy suggests a more complex role for RPL36A, indicating that elevated expression in tumours may be involved in tumour‐suppressive mechanisms rather than directly correlating with poor prognosis." (PMID 40008552, 2025). "Moreover, we identified four putative tumor-specific cryptic peptides from ZYG11A, RPL36A-HNRNPH2, CLIC1 and RPL31 that were decreasingly presented upon MAPKi in SK-Mel-28 wt but were unaffected in SK-Mel-28 dr cells, indicating a direct link to MAPK signaling." (PMID 39835134, 2024).
RPL36A also shares sentences with these, for which no sentence is quoted: Oral Squamous Cell Carcinoma (3 papers); colon cancer (1); Fabry disease (1); glioblastoma (1); jejunal cancer (1); lung adenocarcinoma (1); pancreatic cancer (1); renal clear cell carcinoma (1).